FGF12 (fibroblast growth factor 12)
Description:
Involved in nervous system development and function. Involved in the positive regulation of voltage-gated sodium channel activity. Promotes neuronal excitability by elevating the voltage dependence of neuronal sodium channel SCN8A fast inactivation.
Synonyms: FGF12B; FHF1; DEE47; EIEE47
Tractability: No criterion of Open Targets' tractability assessment is met for any kind of drug.
Gene: Protein-coding gene on chromosome 3 (192,139,390 to 192,767,764, reverse strand). Ensembl gene ENSG00000114279.
Subcellular location: Nucleus
Subcellular location (Human Protein Atlas): Nucleoplasm; Cytosol
Pathways (Reactome):
Muscle contraction: Phase 0 - rapid depolarisation
Gene Ontology:
Molecular function: protein binding; growth factor activity; sodium channel regulator activity; transmembrane transporter binding
Biological process: regulation of neuronal action potential; regulation of voltage-gated sodium channel activity; cardiac muscle cell action potential involved in contraction; cell-cell signaling; heart development; nervous system development; neural crest cell development; neurogenesis; regulation of sodium ion transmembrane transport; ribosome biogenesis; signal transduction
Cellular component: nucleolus; nucleus; cytoplasm; extracellular region
Genetic constraint (gnomAD): Loss-of-function variants: 6 observed, 12.71 expected, observed/expected ratio (o/e) 0.47, 90% interval 0.26 to 0.93. The synonymous counts are far from expectation, so gnomAD's model fits this gene poorly and the ratio says little. Missense variants: 113 observed, 147.01 expected, observed/expected ratio (o/e) 0.77, 90% interval 0.66 to 0.9. Synonymous variants: 34 observed, 52.92 expected, observed/expected ratio (o/e) 0.64, 90% interval 0.49 to 0.86.
Gene-disease validity (ClinGen):
ClinGen rates the evidence that FGF12 causes each of these diseases.
genetic developmental and epileptic encephalopathy (autosomal dominant): Definitive. A complex neurodevelopmental disorder characterized by a range of developmental delays and epileptic encephalopathy phenotypes.
Brugada syndrome (autosomal dominant): Disputed. A genetically heterogeneous condition characterized by complete or incomplete right bundle branch block accompanied by ST elevation in leads V1-V3.
Homologues: Orthologues: chimpanzee FGF12 (98% identical), dog FGF12 (98% identical), guinea pig FGF12 (98% identical), macaque FGF12 (98% identical), mouse Fgf12 (98% identical), rabbit FGF12 (98% identical), rat Fgf12 (98% identical), pig FGF12 (97% identical), tropical clawed frog fgf12 (93% identical), zebrafish fgf12a (88% identical), zebrafish fgf12b (83% identical). Paralogues in human: FGF14 (74% identical), FGF13 (68% identical), FGF11 (57% identical), FGF3 (29% identical), FGF20 (28% identical), FGF9 (28% identical), FGF16 (27% identical), FGF5 (27% identical), FGF6 (27% identical), FGF10 (27% identical), FGF4 (27% identical), FGF1 (26% identical), and 9 more.
Diseases named in the same sentence as FGF12 in open-access papers:
FGF12 is named in the same sentence as 75 diseases in open-access papers, as found by Europe PMC text mining. Sharing a sentence is not in itself a finding about the gene and the disease. The quoted sentences say what the papers report.
epilepsy (10 papers, 2019 to 2026). A brain disorder characterized by episodes of abnormally increased neuronal discharge resulting in transient episodes of sensory or motor neurological dysfunction, or psychic dysfunction. "We propose that the FGF12 variant contributes to both epilepsy and ictal asystole in our patient, possibly via enhanced parasympathetic activation during seizures." (PMID 40897676, 2025). "We report the first known case of a 9‐year‐old male with early‐onset epilepsy, syncope, and ictal asystole–requiring pacemaker implantation at the age of seven–associated with a pathogenic variant in FGF12." (PMID 40897676, 2025). "This study demonstrates biallelic intragenic structural variations and a homozygous single-nucleotide variant in FGF12 cause epilepsy as a new loss-of-function mechanism of FGF12 in humans." (PMID 37286232, 2023). "Functional analyses of FGF12 have shown that the gain-of-function (GOF) effect of the missense variant on NaV causes epilepsy through enhanced modulation of channel inactivation gating, increasing neuronal excitability." (PMID 37286232, 2023). "In FGF12, the missense variant R to H in its gene product, is the cause for early onset epilepsy." (PMID 34086756, 2021). "Only one patient with a small chromosomal duplication involving FGF12 has been reported, who showed similarities with the phenotype in patients with an intragenic mutation, including drug‐resistant epilepsy, severe DD/ID, cerebellar ataxia, and feeding difficulties." (PMID 32524056, 2020). "One patient had a microdeletion, classified here as possibly pathogenic, which includes STAG1, now linked with epilepsy as a cohesinopathy, and one patient carried a de novo intragenic duplication in FGF12 in which SNVs have recently been reported in patients with epileptic encephalopathies." (PMID 30866059, 2019). "We aim to expand the phenotypic spectrum of FGF12-related epilepsy with emphasis on precision therapy." (PMID 42185328, 2026). "In summary, we expand the phenotypic spectrum of FGF12-related epilepsy and discuss the role of early precision therapy in developmental and epilepsy outcomes." (PMID 42185328, 2026). "Subjects 25 and 52 had deletions involving FGF12 and SEMA6B, two known genes associated with ASD and epilepsy." (PMID 39769462, 2024). "We report three additional individuals from two families with a (partial) duplication of FGF12 to further confirm the epilepsy/ID phenotype and to further compare this with the intragenic mutation cases." (PMID 32524056, 2020). "Most of patients with FGF12 pathogenic missense variants presented with drug‐resistant epilepsy and EEG showing mainly multifocal nonspecific abnormalities." (PMID 40838839, 2025). "Point mutations in FGF12 and FGF13 (aka FHF1 and FHF2) cause epilepsy and intellectual disability." (PMID 40662358, 2025). "FGF12 heterozygous recurrent missense variants with gain-of-function or heterozygous entire duplication of FGF12 are known causes of epilepsy, but biallelic SNVs/SVs have never been described." (PMID 37286232, 2023). "In addition, entire FGF12 duplication has been suggested to cause severe epilepsy, implying a pathomechanism similar to the GOF effect of FGF12." (PMID 37286232, 2023). "We identified biallelic intragenic SVs and a homozygous SNV in FGF12, which have never been reported in association with epilepsy." (PMID 37286232, 2023). "The authors suggested a relation with the FGF12 duplication and the epilepsy phenotype." (PMID 32524056, 2020).
Epileptic encephalopathy (7 papers, 2018 to 2025). A condition in which epileptiform abnormalities are believed to contribute to the progressive disturbance in cerebral function. "This phenotype aligns with previous reports, where FGF12 variants were shown to cause Developmental and epileptic encephalopathy 47, frequently manifesting as EIDEE." (PMID 41153369, 2025). "Pt 3, who suffered from intractable epilepsy and progressive cognitive decline, was diagnosed with epileptic encephalopathy 47 with a heterozygous FGF12 mutation." (PMID 33233562, 2020). "Thus, our case further supports the role of FGF12 in early-onset epileptic encephalopathy, reinforcing the association with focal EEG abnormalities and structural brain changes." (PMID 41153369, 2025). "In this study, we applied LRS to investigate the structural organization of recurrent intragenic microduplications in FGF12 and their effects on transcription in two patients with developmental and epileptic encephalopathy (DEE), both harboring an overlapping phenotype and specific EEG features." (PMID 40838839, 2025).
developmental and epileptic encephalopathy (6 papers, 2020 to 2026). An epilepsy associated with developmental impairment that may be due to either the underlying etiology or the superimposed epileptic activity, or both. "Fibroblast growth factor-12 (FGF12) variants have been associated with developmental and epileptic encephalopathy (DEE) with evidence of modulation of voltage-gated sodium channels Nav1.2 and Nav1.6." (PMID 42185328, 2026). "A recurrent de novo heterozygous missense variant, [c.155G>A p.(Arg52His)] of FGF12 has been reported in individuals with developmental and epileptic encephalopathy (DEE) and cerebellar atrophy (#617166; MIM)." (PMID 37286232, 2023). "We discovered biallelic intragenic structural variations (SVs) in FGF12 by applying long-read whole genome sequencing to an exome-negative patient with developmental and epileptic encephalopathy (DEE)." (PMID 37286232, 2023). "Within the cohort of patients experiencing developmental and epileptic encephalopathy (DEE), WES has revealed genetic variants in novel genes (FGF12, GABBR1, GABBR2, ITPA, KAT6A, PTPN23, RHOBTB2, SATB2) and candidate epilepsy-associated genes (CAMTA1, FAT3, GABRA6, HUWE1, PTCHD1)." (PMID 39523358, 2024).
Ataxia (5 papers, 2018 to 2025). Ataxia refers to impaired coordination of voluntary muscle movement. "Intragenic mutations in FGF12 are associated with intractable seizures, developmental regression, intellectual disability, ataxia, hypotonia, and feeding difficulties." (PMID 32524056, 2020). "The phenotypic spectrum of the previously reported FGF12-related disorders includes tonic seizures, ID, speech problems, autistic features, and ataxia." (PMID 37286232, 2023). "In a recent study, FGF12 single-KO mice showed no phenotype, while FGF12/FGF14 double-KO mice developed severe ataxia and decreased neuronal excitability." (PMID 30065296, 2018).
gastric cancer (5 papers, 2012 to 2023). A primary or metastatic malignant neoplasm involving the stomach. "FGF12 expression has been found to be increased in the diffuse type of gastric cancer and downregulated in breast cancer samples from patients with a pathological complete response (pCR) following chemotherapy." (PMID 31850198, 2019). "Among these cytokines, Notch‐3, galectin‐8, EphA1, epiregulin, and FGF‐12 have been reported to be upregulated in gastric cancer." (PMID 30873760, 2019).
Intellectual disability (5 papers, 2020 to 2025). "The phenotype of FGF12/FHF1 DEE comprises intractable seizures with onset in the first days or weeks of life, intellectual disability, and behavioral disturbances with mild cerebral and/or cerebellar atrophy observed with brain magnetic resonance imaging." (PMID 37654020, 2024).
Brugada syndrome (4 papers, 2017 to 2023). "FGF12 is a candidate gene for Brugada syndrome and has been described in association with posterior urethral valves with duplication/triplication in FGF12." (PMID 29216221, 2017). "Similarly, while the gene FGF12 is currently included in diagnostic panels, a PubMed search for “FGF12 AND Brugada syndrome” on October 7, 2019 resulted in only two results: a review and a study in which a variant in FGF12 was found in a single patient." (PMID 32121523, 2020). "A protein–protein interaction associated with Brugada syndrome and sudden death is formed between FGF12 (Fibroblast growth factor 12) and SCN5A (sodium voltage-gated channel alpha subunit 5) proteins." (PMID 38254640, 2023). "FGF12 has also been suggested as a candidate gene for Brugada syndrome, a cardiac arrhythmia channelopathy." (PMID 29216221, 2017).
prostate carcinoma (4 papers, 2015 to 2025). A carcinoma that arises from epithelial cells of the prostate gland. "Transcriptomic analyses of patient biopsies, patient-derived xenografts, and prostate cancer cell models consistently demonstrated elevated FGF12 expression in t-NEPC, which was further validated by immunohistochemistry in archival specimens." (PMID 41294881, 2025). "TUBB2B and FGF12 have been suggested to play vital functions in prostate cancer, neuroblastoma, and esophageal squamous cell carcinoma; however, their roles in HBV-related GC development have never been documented and merit further investigations." (PMID 35592651, 2022).
Arrhythmia (3 papers, 2017 to 2023). Any cardiac rhythm other than the normal sinus rhythm. "Among them, FGF12 has been reported to associate with arrhythmias." (PMID 37497545, 2023). "Because changes in sodium channel function are important in the pathogenesis of idopathic VT and other inherited arrhythmias, we supposed that variations in FGF12 may be associated with VT/idopathic VT." (PMID 28775062, 2017). "Thus, mice may be more “protected” than humans to CaM depletion–induced NaV1.5-mediated arrhythmias because of expression of FGF13 rather than FGF12." (PMID 32870823, 2020).
cardiac hypertrophy (3 papers, 2022 to 2023). "The hierarchical cluster heatmap and Venn diagram indicated that 5 of 22 FGF genes (FGF1, FGF5, FGF12, FGF16, and FGF18) were associated with myocardial hypertrophy." (PMID 36871047, 2023).
esophageal squamous cell carcinoma (3 papers, 2012 to 2025). Esophageal squamous cell carcinoma (ESCC) is a type of esophageal carcinoma (EC) that can affect any part of the esophagus, but is usually located in the upper or middle third. "Elevated FGF12 expression has been observed in gastric cancer and esophageal squamous cell carcinoma (ESCC)." (PMID 41294881, 2025).
bladder cancer (2 papers, 2012 to 2023). "Recently, FGF11, as part of a six-gene signature, has been linked to a worse prognosis in bladder cancer, and macrophage-specific FGF12 accelerates the development of liver fibrosis in mice." (PMID 37108717, 2023). "In the future, liver fibrosis and bladder cancer may be treated with therapeutic methods that block macrophage FGF12 and FGF11 expression." (PMID 37108717, 2023).
Cerebellar atrophy (2 papers, 2024 to 2025). Cerebellar atrophy is defined as a cerebellum with initially normal structures, in a posterior fossa with normal size, which displays enlarged fissures (interfolial spaces) in comparison to the foliae secondary to loss of tissue. "Patients carrying FGF12 variants were more frequently observed to have focal epileptiform discharges and cerebellar atrophy." (PMID 41153369, 2025).
liver fibrosis (2 papers, 2023 to 2025). "Fibroblast growth factor 12 (FGF12) induces a macrophage phenotype switch from Ly6Clo to Ly6Chi by inhibiting JAK/STAT signaling pathways in BDL- and CCl4-induced liver fibrosis." (PMID 41479922, 2025).
osteosarcoma (2 papers, 2017 to 2021). A usually aggressive malignant bone-forming mesenchymal neoplasm, predominantly affecting adolescents and young adults. "Recent studies have shown that also FGF12 has anti-apoptotic properties in the osteosarcoma U2OS cell line overexpressing FGFR1 (U2OS-R1), but this has not yet been linked to drug resistance." (PMID 34830951, 2021). "Vitamin D mediated down regulation of FGF12 mRNA expression in microarray gene expression studies supports the neoplastic role of FGFs in osteosarcoma pathobiology as it stimulates proliferation, extra cellular matrix remodeling, inflammation, and angiogenesis." (PMID 28300755, 2017).
pancreatic cancer (2 papers, 2012 to 2021). "Of note, a recent study reported that FGF12 (the homologue of FGF14) have a malignancy- inhibitor effect on pancreatic cancer cell lines." (PMID 34061869, 2021).
prostate tumors (2 papers, 2015 to 2017). "FGF12 was identified as a new potential marker for prostate tumors." (PMID 28316978, 2017).
adenovirus infection (1 paper, 2022). "First, to confirm the overexpression of FGF12 by adenovirus infection, qRT-PCR was carried out." (PMID 36012732, 2022).
Alzheimer disease (1 paper, 2025). A progressive, neurodegenerative disease characterized by loss of function and death of nerve cells in several areas of the brain leading to loss of cognitive function such as memory and language. "Fibroblastic growth factors (FGFs) and their receptors have been implicated in CNS development (Reuss and von Bohlen und Halbach 2003) as well as diverse neurological diseases, e.g., episodic ataxia (FGF14‐related SCA‐27B) and FGF12, which has been reported in Alzheimer's disease (AD)." (PMID 40406903, 2025).
autism spectrum disorder (1 paper, 2020). A spectrum of developmental disorders that includes autism, and Asperger syndrome. "In some of these patients, (mild) ID and/or autism spectrum disorder were reported, suggesting that dosage of FGF12 is important for neurodevelopment." (PMID 32524056, 2020).
cerebrovascular diseases (1 paper, 2024). "Genes related to cardiovascular and cerebrovascular diseases annotated by the PI3K-Akt signaling pathway included Fgf12, Fgfr1, PDGFA, and PDGFRα." (PMID 38195688, 2024).
colorectal tumors (1 paper, 2017). "Methylation of FGF12 has been reported in colorectal tumors but not in matched controls as has methylation of ASCL1." (PMID 28278225, 2017).
COVID-19 (1 paper, 2023). A disease caused by infection with severe acute respiratory syndrome coronavirus 2. "By applying COVIDanno, we identified multiple important genes associated with COVID-19 symptoms, such as UGT2A1, FGF12." (PMID 37497545, 2023). "However, in autopsies of COVID-19 patients, no significant changes in FGF12 expression were observed in cardiomyocytes." (PMID 37497545, 2023).
depression (1 paper, 2018). "However, to date no published study have reported the association between FGF20 gene and depression; although some studies have reported association between another FGF system transcripts, such as FGF2, FGF12 and FGFR2 with major depressive disorder." (PMID 30241547, 2018).
endometrial cancer (1 paper, 2017). Primary or metastatic malignant neoplasm involving the endometrium (mucous membrane that lines the endometrial cavity). "It is appealing to suggest that ASCL1 and FGF12 methylation might have diagnostic potential (ability to discriminate between tumor and normal tissues) in both colorectal and endometrial cancer or reflect similarities in the biology underlying these cancer types." (PMID 28278225, 2017).
leiomyosarcoma (1 paper, 2024). An uncommon, aggressive malignant smooth muscle neoplasm, usually occurring in post-menopausal women. "Moreover, a comparative analysis of FGF12 and KLHL29 expression across different sarcoma subtypes and leiomyosarcomas (LMS) revealed a significant difference in KLHL29 expression between HG-ESS and LG-ESS and LMS." (PMID 39676856, 2024).
lymphangioma (1 paper, 2007). A benign lesion composed of dilated lymphatic channels. "We have observed high expression of FGF-12 and TGF-α in lymphangioma LECs, but the significance of this finding remains to be studied." (PMID 17584927, 2007).
melanoma (1 paper, 2022). A malignant, usually aggressive tumor composed of atypical, neoplastic melanocytes. "On the other hand, the top downregulated genes formed 4 subgroups and were related to melanogenesis (Wnt5a, Mitf, Pomc, Mc1r, Kit), melanoma (Fgf9, Fgf12, Fgf2), MAPK signaling pathway (Ncam1, Prkcb, Map3k4, Pla2g4a, Mapk14, Mapk11), and aging (Tgfbr1, Il6, Nox4)." (PMID 36555664, 2022).
opioid use disorder (1 paper, 2026). A substance-related disorder that involves the recurring use of opioids despite negative consequences. "By identifying Fgf12 as a novel candidate gene and highlighting its epistatic interaction with Oprm1, this study sets the stage for a paradigm shift in our approach to opioid use disorder, from focusing solely on receptor-level pharmacology to embracing complex genetic and signaling networks." (PMID 41487078, 2026). "Two key modulators emerged: a gene on chromosome 10 called Oprm1, which codes for a well-known opioid receptor; and a gene on chromosome 16 that codes for a signaling protein called fibroblast growth factor 12 (Fgf12), which has not previously been linked to opioid use disorder." (PMID 41487078, 2026).